MSLN (mesothelin)
Diseases named in the same sentence as MSLN in open-access papers (continued):
Sharing a sentence is not in itself a finding about the gene and the disease.
tumor (continued). "CRISPR/Cas9 technology has also been used to knock out the TGF-β receptor II (TGFBR2) and render anti-MSLN CAR T cells resistant to the adverse effect of TGF-β signaling, thus rescuing their proliferation potential, potency and anti-tumor activity in MM mouse models." (PMID 33588928, 2021). "TEXs originate from tumour cells and may contain many tumour-specific antigens, such as melan-A, gp 100, carcinoembryonic antigen (CEA), and mesothelin." (PMID 33789758, 2021). "In immunocompetent mice, we found that selective depletion of FRβ+ TAMs prior to the administration of mesothelin-specific CAR-T cells significantly improved engraftment and expansion of tumor-specific CAR-T cells and promoted a more robust endogenous T cell recruitment." (PMID 33563975, 2021). "We also show that inhibition of YAP1/TEAD interaction interferes with the expression of AREG, CTGF, CYR61, and MSLN suggesting that YAP1 transcriptional activity may affect the development and persistence of a fibrotic tumor microenvironment." (PMID 32054505, 2020). "Similarly, the bivalency of MG1122-B for tumor antigen promotes high binding avidity toward tumor cells, and its tumor targeting was superior to that of MG1122-A, which binds monovalently to MSLN." (PMID 32143496, 2020). "The results in mouse models have indicated that anti-MSLN CAR-T and anti-hPSMA CAR-T cell therapy, in combination with anti-PD1 antibody, could improve the activity of CAR-T cells and enhance anti-tumor activity." (PMID 32766150, 2020). "MSLN contributes to cell proliferation and resistance to apoptosis, and by activating matrix metalloproteases 9 (MMP-9) and MMP-7, it can induce tumor cell migration and invasion." (PMID 35582441, 2020). "Further studies in a clinically relevant orthotopic mouse model that recapitulated the MPM biology showed that the ectopic overexpression of mesothelin promoted tumor invasion and significantly decreased survival, compared to mice with MSLN-negative tumors." (PMID 32882916, 2020). "Elizabeth Jaffee’s team was the first to identify MSLN as immunogenic protein, using GVAX (GM-CSF gene-transfected tumor cell vaccine), which originates from irradiated PDAC cells genetically engineered to secrete the granulocyte-macrophage colony-stimulating factor (GM-CSF)." (PMID 32517181, 2020). "We also established intraperitoneal xenografts for BG1 and OVCAR4 cell lines (both are MSLNlow) with and without MSLN overexpression and observed again that tumor burden and dissemination was enhanced through MSLN overexpression." (PMID 32612258, 2020). "To demonstrate specificity for tumor antigens we included control groups of T cells transduced either with tumor-irrelevant CAR genes (P28z, targeting the Prostate-Specific Membrane Antigen21), or TCR genes (MSLN-TCR, specific for Mesothelin22)." (PMID 33247092, 2020). "The role of mesothelin in the development of normal cells is not known, whereas, in cancer cells, mesothelin promotes tumor progression by interacting with other membrane proteins, such as CA125." (PMID 32731396, 2020). "The same group also developed a CXCL11/mesothelin CAR that increased intratumoral levels of CXCL11 but did not improve anti-tumor activity." (PMID 30804938, 2019). "A potential explanation of this result could be an indirect effect of MesobsFab on the MSLN-driven secretion of matrix metalloproteases, notably MMP-7 and MMP-9 which have been described as promoting tumor invasion." (PMID 31354732, 2019). "Therefore, to kill tumor cells expressing MSLN and integrin αvβ3, FHBM can be used as a switch to tune the cytotoxicity of CD8+ T cells expressing an sdCAR specific for MSLN and the FITC part of FHBM." (PMID 29558951, 2018). "Nevertheless, for monitoring purposes that are independent of the availability of tumor material or pulsed DCs we analyzed mesothelin-specific T cells in peripheral blood during treatment." (PMID 30245692, 2018).
tumor (continued). "These amplifying effects of iNKT cells were detected in various tumor cells regardless of the expression level of MSLN." (PMID 30558663, 2018). "Based on our data, a novel type of CAR-T cells, dCAR-T cells, can exert significant cytotoxicity only in the presence of cognate tumor cells (AsPC-1) expressing both CEA and MSLN, which is comparable with that obtained with conventional CAR-T cells and alleviates “on-target, off-tumor” toxicity." (PMID 30103775, 2018). "In this study, we demonstrated the effect of shed mesothelin on the tumor targeting and tumor microdistribution of anti-mesothelin mAb amatuximab in A431/H9 tumor using anti-Lewis-Y B3 as a negative control." (PMID 29720923, 2018). "To investigate if the shed mesothelin in the ECS of tumor could affect the penetration of 89Zr-amatuximab, we performed the autoradiography of tumor segments at 48 h p.i. immediately after the completion of the PET imaging studies." (PMID 29720923, 2018). "Co-expression of a dominant-negative PD-1 receptor with mesothelin-targeted CAR T cells has also been shown to render these cells resistant to PD-1-induced inhibition and to significantly improve their in vivo anti-tumor efficacy following a single administration." (PMID 30559740, 2018). "LMB-100 specifically induces PSI in MSLN-expressing tumor cells but has no activity against the cells in the tumor microenvironment because they do not express hMSLN." (PMID 30384408, 2018). "We next examined whether the proliferation of dCAR-T cells was dependent upon the cognate tumor cells expressing both CEA and MSLN." (PMID 30103775, 2018). "N-cadherin, mesothelin, and calretinin MPM biomarker mRNA and protein expression was determined and decreasing calretinin expression reflected the evolution of the tumor." (PMID 29527515, 2018). "MSLN and MUC16 binding has been reported to enhance tumor cell proliferation and metastasis." (PMID 29738555, 2018). "To achieve this goal, we used a nude mouse model implanted with A431/H9 tumor that overexpresses both shed MSLN (5 million Ag molecules/cell) and nonshed Lewis-Y (4 million Ag molecules/cell)." (PMID 29720923, 2018). "Mesothelin has broad potential as a novel tumor target for both diagnosis and therapy, yet no MSLN-targeting molecules are currently FDA approved." (PMID 29738555, 2018). "The mouse model implanted with A431/H9 tumor, which expresses both shed mesothelin and nonshed Lewis-Y antigen, provided an ideal system to compare the biodistribution and PET imaging profiles of the two mAbs." (PMID 29720923, 2018). "The results validate that non-antibody proteins can be engineered to bind to tumor biomarker mesothelin, and encourage the continued development of engineered variants for applications such as targeted diagnostics and therapeutics." (PMID 29738555, 2018). "Compared with the first generation of CAR-T cells, sdCAR-T cells designed here are not activated in the presence of FHBM and tumor cells that express integrin αvβ3 and do not express MSLN (such as CEA+ K562 cells)." (PMID 29558951, 2018). "The most common tumor targets are cell surface molecules, such as EGFR, HER2, Mesothelin, CD19, or CD20 whose cell membrane localization, and sometimes tumor-specific expression, or overexpression in comparison to healthy tissues, makes them suitable for antibody-based therapy." (PMID 29946318, 2018). "Since tumor sphere formation commonly serves as one of the indicators of cancer stem-like cell (CSC) formation, the results of this study also suggest the role of MSLN in CSC regulation, which is supported by our subsequent studies." (PMID 28288645, 2017). "Expression of mature, surface-bound mesothelin protein was found to bein human GBM defined by immunofluorescence microscopy, and on freshly isolated, single cell suspension of GBM tumor cells and GBM tumor cell lines, determined by based on flow cytometric analysis." (PMID 29113296, 2017).
tumor (continued). "Additionally, Mesothelin contributes to further understanding of the biology of MPM, because it participates in cell adherence, cell proliferation and tumor invasion of MPM." (PMID 28507279, 2017). "Finally, mechanistic studies revealed that knockdown of MSLN reversed EMT and attenuated stem cell properties, in addition to inhibiting tumor growth and metastasis." (PMID 28288645, 2017). "Although the biologic function of mesothelin is not very clear, researchers have found that it plays a role in the survival, proliferation, and migration of tumor cells." (PMID 27514374, 2016). "More specifically, by taking advantage of the high affinity interaction between mesothelin and MUC16, we recently designed a mesothelin/TR3 fusion protein, designated Meso-TR3, in order to tether our therapeutic to the MUC16 biomarker located on the tumor cell membrane." (PMID 27120790, 2016). "Mesothelin is not necessarily a tumor progression factor, and indeed mesothelin overexpression inhibited tumor growth in immunocompetent mice." (PMID 26931187, 2016). "Although the tumor to blood ratio was no more than 1, the ratio of 64Cu-DOTA-mAb in MSLN-positive tumors was significantly higher than that in MSLN-negative PANC-1 tumor." (PMID 25883990, 2015). "In contrast, novel drugs are becoming available that target over-expressed tumor specific antigens such as MSLN that have no clear role in tumor genesis." (PMID 26172299, 2015). "Tumor regressions were observed in tumor models where only 20% of the cells expressed mesothelin, which suggests that the non-mesothelin cells were killed by the release of the DM4 metabolite from the mesothelin expressing cells." (PMID 25339341, 2015). "MSLN also binds CA-125/MUC16 with very high affinity and may contribute to the adhesion of tumor cells in peritoneal metastasis." (PMID 25506917, 2014). "Additionally, we have shown that mesothelin and NKG2D can be used as tumor-homing modules in chimeric proteins, delivering the therapeutic proteins to tumor loci." (PMID 25531529, 2014). "In the present study, to determine whether serum levels of N-ERC/mesothelin correlated with tumor size, we measured N-ERC/mesothelin levels in rats bearing PDA." (PMID 25347530, 2014). "Although MTBHsp70 also binds to these MSLN-expressing tumor cells, the level of binding is not significantly different from background (p = 0.187 for BR5FVB1 cells, and p = 0.086 for 40L cells)." (PMID 24565018, 2014). "In these two studies, a PC cell vaccine induced a CD8+ T cell response, specific to mesothelin, regardless of HLA match between the tumor vaccine and recipient—demonstrating that cross-priming had occurred." (PMID 23509731, 2013). "The model that included the three biomarkers (MUC1, MSLN, and MUC2) was superior to the model including four conventional pathologic features (lymph node status, histologic grade, tumor size, and resection margin status), although the difference just missed statistical significance (p = 0.07)." (PMID 22792233, 2012). "The Mesomark Assay has been evaluated in a single study of PD; the study was not powered to test prognostic capability and did not compare levels with tumor MSLN expression." (PMID 22792233, 2012). "Both lines (NCI-M-03 and NCI-M-13) contain mesothelin-positive tumor cells and mesothelin-negative cells isolated from the same tumor microenvironment." (PMID 21305058, 2011). "Cell surface attachment of mesothelin depends on a glycophosphatidylinositol (GPI) anchor but, to our knowledge, the release mechanism of mesothelin from tumor cells has not been described." (PMID 22163010, 2011). "Many tumor antigens are heavily glycosylated, such as tumoral mucins, and/or attached to tumor cells by mannose residue-containing glycolipids (GPI anchors), as for example mesothelin and the family of carcinoembryonic antigen (CEA)." (PMID 22163010, 2011).
tumor (continued). "We conclude that the absence of co-immunoprecipitation of exosomal proteins with tumor-released mesothelin demonstrates that mesothelin does not reside in tumor-released exosomes." (PMID 22163010, 2011). "As the effect of cytotoxic drugs is influenced by histological stage and tumour volume, we analysed if the expression level of mesothelin could correlate with the chemoresponse of EOC patients with similar histological stages and residual tumour sizes." (PMID 19293794, 2009). "Our findings imply that cancer cells containing greater levels of mesothelin can resist cytotoxic drug-induced apoptosis and will continue to progress, unlike other tumour cells that fail to express mesothelin." (PMID 19293794, 2009). "The [89Zr]­Zr-2A10-VH-FcLALAPG mutant, whichdemonstrated higher tumor accumulation and reduced off-target distributionin HCT116 xenografts relative to those of [89Zr]­Zr-2A10-VH-FcWT and [89Zr]­Zr-2A10-VH-FcGRLR, was furtherassessed in additional MSLN-positive xenograft models." (PMID 41439681, 2026). "This research study results also found that systemic administration of α-GalCer or Zoledronate could enhance the anti-tumor effect of MSLN/CD3 bsAb, and no obvious toxicity was observed." (PMID 39995672, 2025). "Furthermore, some DT CAR-T designs co-targeting MSLN and NKG2D ligands induce the secretion of bispecific T-cell engagers (BiTEs) that recruit endogenous T cells and natural killer (NK) cells into the tumor site, amplifying immune infiltration even in immunologically “cold” TNBC models." (PMID 41348261, 2025). "Although a specific mechanism could not be highlighted suppressing MSLN inhibited cell growth and tumor proliferation in vivo." (PMID 40227616, 2025). "However, focusing the analysis solely on 2 single TAA, mesothelin and WT-1, did not provide a comprehensive view of T-cell specificities necessary to monitor the anti-tumor T-cell response." (PMID 40236706, 2025). "Considering the density of antigen expression, even the level of MSLN expression can be detectable but scattered within a tumor, meaning the tumor is technically MSLN-positive, but the antigen density may not be enough to activate MSLN-CAR T cells effectively." (PMID 40366419, 2025). "Currently, various mesothelin-targeted therapeutic strategies, including anti-mesothelin antibodies, antibody-drug conjugates (ADC), and Chimeric Antigen Receptor T-cell Therapy (CAR-T), have demonstrated promising anti-tumor efficacy in preclinical studies and some early-stage clinical trials." (PMID 41400642, 2025). "Blocking the binding of MSLN and MUC16 may be a promising approach to inhibiting tumor metastasis." (PMID 41400642, 2025). "This approach demonstrated the improved anti-tumour efficacy of PD-1-silenced, MSLN-targeted CAR-T cells across multiple cancer models and underscores the therapeutic potential of targeting immune checkpoints like PD-1 to boost CAR T cell therapies against various tumours." (PMID 39596267, 2024). "However, this approach yielded different results in the CAPAN-2 model, where the most favorable response was observed with a single 4-Gy fraction coupled with 1 × 105 anti-mesothelin CAR-T cells, maintaining tumor volumes below 500 mm3 and ensuring mouse survival for up to 75 days post-implantation." (PMID 39445067, 2024). "Exposure to treosulfan and fludarabine did not impact MSLN-CAR T cells effectors functions (degranulation and cytokine production) or mitochondrial defects, while combination of treosulfan and fludarabine decreased MSLN-CAR T cells anti-tumor killing in normoxia but not in hypoxia." (PMID 38954005, 2024). "Exposure to treosulfan and fludarabine did not impact MSLN cell surface expression on SKOV3 and OVCAR4 suggesting that these two drugs do not negatively impact this tumor antigen expression and, subsequently, the capacity for MSLN-CAR T cells to bind MLSN and kill tumor cells." (PMID 38954005, 2024).
tumor (continued). "To determine whether MET is involved in MSLN-regulated tumor cell penetration of the BBB, we knocked down MET in PC9-BrM cells with siRNA and then overexpressed MSLN in PC9-BrM cells in which we had previously knocked down MSLN (PC9-BrM-SH2)." (PMID 38570866, 2024). "Mouse models have prompted the hypothesis that MSLN expression can lead to faster tumour growth, although this is not observed universally, and may depend upon the tumour location and the presence of a functioning immune system." (PMID 37040900, 2023). "In MDA-MB-231 tumour-bearing mice, the signal detected in the tumour in the presence of anti-MSLN Nb was not significantly different from that detected with the irrelevant Nb, highlighting the specific tumour capture in relation to the expression level of mesothelin." (PMID 37388728, 2023). "Staining done 7 days post-T cell injection showed the tumors to be devoid of GFP+ CAR T cell infiltration in mice treated with MigR control and Meso-CAR T cells which notably had no impact on either FAP+ stromal cell or Mesothelin+ tumor cells even by day 7 post-T cell administration." (PMID 37607999, 2023). "The target antigen MSLN is not specifically expressed on the surface of tumor cells, which may lead to off-target effects." (PMID 36900151, 2023). "Moreover, the eradication of LCAR-M23 is MSLN density dependent, translating into strong cytotoxicity to tumour cells with high expression levels of MSLN and weak or no cytotoxicity to cells with low expression levels of MSLN." (PMID 36166071, 2023). "While MSLN positivity (≥ 5% of tumour) was not an independent prognostic marker, the degree of MSLN expression, measured by H‐score as a continuous variable or an elevated H‐score ≥ 33, and a 2+/3+ staining intensity, were independent prognostic markers of improved survival." (PMID 37040900, 2023). "While higher serum SMRP is related to a poorer clinical outcome, SMRP levels may reflect tumour size or the extent of enzymatic shedding rather than the degree of surface MSLN expression." (PMID 37040900, 2023). "In addition to TAMs correlation with tumor progression, there are some immunomodulatory proteins that have been reported in the last years to be overexpressed in various types of cancers, especially CD80 and mesothelin (MSLN)." (PMID 36387279, 2022). "Anti-MSLN antibody-drug conjugate anetumab ravtansine is composed of a human anti-MSLN IgG1 and a maytansine derivative tubulin inhibitor DM4, which shows selective and potent antitumor activity in xenograft tumor models." (PMID 36268019, 2022). "The cell surface antigen mesothelin was found to be overexpressed in 67% of TNBC samples and is considered a potential target because of its involvement in the activation of intracellular pathways including MAPK, NFкB, and PI3K, resulting in tumor cell proliferation and resistance to apoptosis." (PMID 35814023, 2022). "Although the expression of MSLN in tumors makes it a potential therapeutic target, its mechanism of action is still unclear, especially its correlation with immune cells infiltration in the tumor microenvironment has not been investigated." (PMID 35692779, 2022). "Subsequently, we investigated whether CCL19 expression in the mesoCAR-N19 cells can be induced by mesothelin-positive or negative tumor cells." (PMID 35990619, 2022). "A previous study reported that combination of anti-mesothelin CAR-T cells with PD-L1 CAR-T cells did not repress tumor growth synergistically in patient-derived xenograft (PDX) because PD-L1 CAR-T killed mesothelin CAR-T cells by targeting its endogenous PD-L1 antigen." (PMID 35317524, 2022). "In addition, we found that MSLN-CAR T cells maintained transient antitumor activity but failed to achieve tumor control, possibly due to the limited antigen expression in SNU119 cells and the low percentage of CD3+ cells in the peripheral circulation." (PMID 34803504, 2021).